MYC (MYC proto-oncogene, bHLH transcription factor)
Diseases named in the same sentence as MYC in open-access papers (continued):
Sharing a sentence is not in itself a finding about the gene and the disease.
gastric cancer (405 papers, 2010 to 2026). A primary or metastatic malignant neoplasm involving the stomach. "We further investigated the biological effects of FMR1 on gastric cancer cell proliferation, migration, and invasion in vitro, and elucidated the underlying mechanism involving c-MYC signaling." (PMID 41184982, 2025). "Our experimental results reveal that HECTD3 facilitates the malignant proliferation of gastric cancer by mediating K29 site-linked polyubiquitination of c-MYC." (PMID 35397617, 2022). "In this review, we discuss the mechanisms of action underlying PVT1 oncogenic role in colorectal and gastric cancer such as MYC upregulation, miRNA production, competitive endogenous RNA (ceRNA) function, protein stabilization, and epigenetic regulation." (PMID 32083000, 2020). "Expression of the three studied kinases was also associated with MYC oncogene expression, a possible biomarker for gastric cancer." (PMID 26460485, 2015). "Expression of SRC, LYN and CKB in gastric cancer is significantly associated with tumor invasion and lymph node and distant metastases, as well as with MYC expression, which is also a possible biomarker for GC." (PMID 26460485, 2015). "Amplification at 8q24.21 is significant because the oncogene MYC harbored in this region is known to be associated with many cancers, including gastric cancer." (PMID 26035356, 2015). "Clinicopathological characteristics, MYC immunoreactivity, DNA methylation and point mutations in gastric cancer samples." (PMID 23717612, 2013). "However, another study showed that MYC activated in Epstein-Barr virus-associated gastric cancer elevated FTO expression by binding to the FTO promoter." (PMID 39744011, 2024). "Notably, mutational gains and amplifications of the MYC gene, which can be found in all gastric cancer subtypes, are associated with early progression of intestinal metaplasia to gastric cancer." (PMID 38177458, 2024). "CBX3 is a putative target of MYC and may serve as a new diagnostic biomarker and a potential target for immunotherapy in gastric cancer." (PMID 36304306, 2022). "Interestingly, like N14-77 polyps, stomach cancers that harbor STAMBPL1 F407fs or K405fs mutation also display upregulation of MYC target genes and downregulation of trafficking genes." (PMID 30018743, 2018). "MYC amplification is associated with the aggressive behavior of gastric cancer cells." (PMID 26360582, 2015). "MYC deregulation due to gene amplification, chromosomal translocation or insertion, mutations, and epigenetic modifications, has been reported in different types of cancers, especially in gastric cancer." (PMID 23717612, 2013). "Additionally, MYC immunostaining was more frequently observed in intestinal-type than diffuse-type gastric cancers and was associated with MYC mRNA expression." (PMID 24053468, 2013). "Because MYC is frequently (~70%) gained or amplified across gastric cancers, we used a transposon vector containing human MYC cDNA as the universal oncogene and adapted sgRNAs to target different tumor-suppressor genes in accordance with their mutation in distinct subtypes of gastric cancer." (PMID 38177458, 2024). "Gastric cancer–associated lncRNA1 (GClnc1) may promote progression of BC via activation of MYC." (PMID 35309945, 2022). "In gastric cancer, it enhances malignancy by upregulating oncogenes such as MYC and suppressing tumor suppressors like KLF2." (PMID 41517663, 2026). "BPTF has been shown to contribute to erlotinib resistance in gastric cancer by regulating the c-MYC/PLCG1/p-Erk axis." (PMID 41602481, 2026). "We then blocked protein synthesis with cycloheximide, and the results showed that FMR1 knockdown markedly accelerated c-MYC degradation in gastric cancer cells." (PMID 41184982, 2025). "It promotes YAP1 transcription by binding to c-MYC in the YAP1 promoter in gastric cancer and T-cells." (PMID 40649881, 2025).
gastric cancer (continued). "Overexpression of RBMS1 in HGC-27 and SGC-7901 cells increased the migration and invasion of gastric cancer cells by binding to the transcription factor MYC and activating the IL-6/JAK2/STAT3 signaling pathway." (PMID 41214391, 2025). "c-MYC also promotes gastric cancer cell proliferation, migration, invasion, and epithelial–mesenchymal transition (EMT) in vitro, as well as tumor growth in vivo, by interacting with and activating downstream lncRNAs." (PMID 41184982, 2025). "Our data indicate that FMR1 promotes the oncogenic properties of gastric cancer cells by directly activating c-MYC.." (PMID 41184982, 2025). "Once in the nucleus, FOXC1 separates from β-catenin, thereby regulating c-MYC transcription and promoting gastric cancer cell proliferation." (PMID 39430239, 2024). "METTL3 was significantly elevated and promoted the proliferation of gastric cancer by regulating the expression of MYC pathway in the post-transcriptional modification." (PMID 39009956, 2024). "Another study demonstrated that 14–3-3ε inhibited gastric cancer (GC) cell proliferation by reducing MYC and CDC25B expression." (PMID 38279176, 2024). "The dysregulation of LHPP expression leads to the upregulation of IGF1R, thereby activating the downstream ITGB1–FAK–SRC/YAP–c‐MYC signaling pathway, resulting in the development and progression of gastric cancer." (PMID 38292328, 2024). "ADAMTS10 was reported to alter the JAK/STAT/c-MYC pathway and reprogram macrophages in gastric cancer, possibly inhibiting cancer progression, and was shown to be a plausible prognostic biomarker." (PMID 39329961, 2024). "It has been reported that FTO can reduce the methylation of MYC in gastric cancer cells and stabilize its expression, ultimately resulting in augmented proliferation, migration and invasion of gastric cancer cells in vitro." (PMID 39744011, 2024). "BRD4 activates c-MYC through transcriptional and epigenetic regulatory mechanisms, thereby increasing the proliferation of gastric cancer cells and inhibiting apoptosis." (PMID 39430761, 2024). "have studied the potential role of miR-561-3p in gastric cancer development, and their finding confirmed that miR-561-3p inhibits cell proliferation and invasion by downregulating c-MYC expression." (PMID 38462658, 2024). "Overexpression of c-MYC promotes the development of gastric cancer through the c-MYC/glycolysis axis." (PMID 37582735, 2023). "BPTF inhibitor increases gastric cancer response to Erlotinib by epigenetically regulating c‐MYC/PLCG1/pErk axis." (PMID 37863665, 2023). "The upregulation of LINC00942 lncRNA in gastric cancer contributes to the higher stability of the MYC mRNA in an N6-methyladenosine-dependent manner by preventing the ubiquitous degradation of RBP MSI2 and consequently promoting chemoresistance." (PMID 37443779, 2023). "has revealed that the IFITM3 can expand malignant progression, promote cancer stemness and chemoresistance of gastric cancer by targeting MET/AKT/FOXO3/c-MYC axis." (PMID 37304304, 2023). "For example, IGF2BP3 promoted the proliferation ability by regulating the expression of MYC through mRNA stabilisation in gastric cancer." (PMID 37743642, 2023). "Overexpression of RUNX3 in an array of gastric cancer cell lines resulted in the reduction of MYC proteins in all tested cell lines." (PMID 37400551, 2023). "Circ-TNPO3 can act as a protein decoy for IGF2BP3, weakening the role of IGF2BP3 in stabilizing MYC mRNA, thereby inhibiting gastric cancer cell migration and proliferation." (PMID 37298373, 2023). "PRMT5 also interacts with c-MYC, which in turn is critical for H4R3me2s in repressing target genes to promote gastric cancer progression." (PMID 35655230, 2022).
gastric cancer (continued). "Our group observed considerable inter- and intra-tumoral heterogeneity between patterns of MYC amplification in the pre-screened study population in line with previous findings in MYC amplified gastric cancer." (PMID 35448150, 2022). "circPRMT5 is highly expressed in gastric cancer patients, and the upregulation of circPRMT5 can promote the expression of oncogene MYC through sponging miR-145 and miR-1304." (PMID 36161608, 2022). "Next, a proximity ligation (PLA) experiment was employed to observe the interaction of HECTD3 and c-MYC in gastric cancer cells." (PMID 35397617, 2022). "After 48 hours, qRT-PCR was used to verify the expression of MYC in gastric cancer cell lines transfected with circABCB10, circABCB10 +miR-1252-5p, and circABCB10 + sh-MYC, respectively." (PMID 34950208, 2021). "Circ-PRMT5 contributed to gastric cancer development through up-regulating MYC via sponging miR-145 and miR-1304." (PMID 33892646, 2021). "The molecular mechanism of circABCB10 regulating the biological function of gastric cancer by competitively binding with miR-1252-5p to affect the expression of MYC has been studied." (PMID 34950208, 2021). "Overexpression of miR-1252-5p and knockdown of MYC reversed the promoting effect of circABCB10 on gastric cancer." (PMID 34950208, 2021). "circABCB10 can promote the proliferation, invasion, and clonal formation of gastric cancer cells by targeting miR-1252-5p and upregulating the expression of MYC." (PMID 34950208, 2021). "Circ-hHBB3 binds HuR and degrades HuR, whereas Circ-TNPO3 competitively binds IGF2BP3 and inhibits the proliferation and metastasis of gastric cancer by regulating the MYC-SNAIL axis, which leads to malignant progression of GC." (PMID 35116058, 2021). "It has been shown that the tissue-specific factor gastrokine-1 stimulates the expression of miR-34a in gastric cancer cells, suppressing the expression of proto-oncogenes MYC and RhoA, which leads to a decrease in the ability of cells to migrate and invade." (PMID 34440124, 2021). "In gastric cancer, miR-1304-5p participates in the circ-PRMT5/miR-145/miR-1304/MYC axis to promote tumor progression and the MYC gene is also associated with ‘double hit’ DLBCL, which indicates an unfavorable prognosis." (PMID 34109978, 2021). "BRD4 has been reported to be able to promote the progression of gastric cancer by regulating c-MYC transcription and epigenetics." (PMID 34876902, 2021). "Some studies have reported that other miRNAs can regulate MYC and further affect the occurrence and development of gastric cancer." (PMID 34950208, 2021). "Further experiments confirmed that miR-145 can regulate c-MYC expression in gastric cancer cell lines." (PMID 34950208, 2021). "And overexpression of MYC can rescue the growth-suppressive effects of FZD7 knockdown in gastric cancer cells." (PMID 33987183, 2021). "Two other circRNAs, circLMTK2 and circ-PRMT5, have been shown to bind miR-150-5p, miR-145, and miR-1304 and increase MYC gene expression in gastric cancer cells." (PMID 34440124, 2021). "AURKA is activated in gastric cancer and it has been demonstrated that AURKA promotes cisplatin resistance in gastric cancer by regulating eIF4E, c-MYC, HDM2." (PMID 32508530, 2020). "Here, we overview the MYC role and its relationship with the microRNAs network in gastric cancer aiming to identify potential targets useful to be used in clinic, not only as biomarkers, but also as molecules for development of promising therapies." (PMID 32150871, 2020). "The positive correlation between MYC and YAP in human gastric cancers also supports the regulation of MYC by YAP, which is an important molecular mediator of gastric tumourigenesis." (PMID 32660514, 2020). "Significant gains of genes ATAD2, DSCC1, FAM91A1, and MYC brought to the enrichment of the Gastric Cancer Network 2 pathway, and ATAD2 is a cancer-associated protein which can also induce the expression of Cyclin D1 and MYC." (PMID 31921654, 2019).
gastric cancer (continued). "MYC overexpression is considered a driver event in gastric cancer (GC), and is frequently correlated with poor prognosis and metastasis." (PMID 31645899, 2019). "For instance, 5‐Aza contributes to the upregulation of miR‐212 in gastric cancer, leading to the inhibition of MYC expression." (PMID 30791232, 2019). "Gene set enrichment analysis (GSEA) revealed gene sets such as “MYC-Targets” is strongly enriched in EphA2high gastric cancer specimens compared with EphA2low specimens." (PMID 30451837, 2018). "The use of siRNA to reduce MYC expression in the three gastric cancer cell line used in this study was very effective, reducing MYC mRNA expression in 73% for AGP01, in 84% for ACP02, and in 77% for ACP03." (PMID 30410872, 2018). "This is an important step towards the understanding of MYC's role in gastric carcinogenesis and an indication of probable new drug targets in stomach cancer." (PMID 30410872, 2018). "Taken together, the comparative analysis of HIF-1α, ANXA1 and MYC expression in human gastric cancer samples confirmed the in vitro data, further indicating a potential functional association between HIF-1α, ANXA1 and MYC in this tumor entity." (PMID 26760764, 2016). "In order to understand if modulation of c-MYC plays also a role in gastric cancer, c-MYC expression studies were performed on cells treated with (+)-JQ1 and PNZ5." (PMID 27259267, 2016). "We found that the expression of β-catenin and its downstream targets CD44, c-MYC, and Cyclin-D3 were significantly up-regulated in gastric cancer cells after treatment with low level of DIM." (PMID 26918831, 2016). "Some malignant tumors with c-MYC overexpression including gastric carcinoma, esophageal squamous cell carcinoma, and soft tissue leiomyosarcoma are associated with poor survival." (PMID 27619912, 2016). "All but one of these cancers had areas with and without clear-cut high level amplification or even areas with normal MYC copy numbers, suggesting that high-level MYC amplification occurs at later stages of gastric cancer progression." (PMID 25649416, 2015). "MYC is amplified and over-expressed in gastric cancer, and its expression increases progressively as the cancer develops." (PMID 26360582, 2015). "Markedly, higher rates was only reported from two small studies finding MYC amplification in 3 of 7 gastric cancers by FISH and in 17 of 33 tumors using less quantitative PCR for CCND1 amplification analysis." (PMID 25649416, 2015). "FBXW7 mutations are common in USC, and also have been shown to increase MYC signaling in gastric cancers." (PMID 26170901, 2015). "Among the genes located on 8q24.21, MYC is known to promote the growth and proliferation of normal gastric cells, and knockdown of MYC restrains the growth and proliferation of gastric cancer cells." (PMID 26360582, 2015). "In contrast, high-level amplification, as indicated by presence of large signal clusters containing more than 10 MYC copies, were found only in 9% of our gastric cancers." (PMID 25649416, 2015). "MYC hypomethylation was more frequently observed in the diffuse-type as compared to the intestinal-type gastric cancer (p = 0.007; OR = 8.554; 95% CI = 01.798–40.695, using diffuse-type as reference group)." (PMID 23717612, 2013). "The understanding of MYC biology is of paramount importance to elucidate its role in the pathogenesis of gastric cancer." (PMID 23717612, 2013). "Our study investigated the relationship between MYC alterations and clinicopathological features in gastric cancers." (PMID 23717612, 2013). "Here, we evaluated the relationship between MYC alterations and clinicopathological features in gastric cancer." (PMID 23717612, 2013). "In vitro studies showed that increased MYC and reduced FBXW7 expression is associated with a more invasive phenotype in gastric cancer cell lines." (PMID 24053468, 2013).
gastric cancer (continued). "Clinicopathological characteristics, MYC mRNA expression, copy number and percentage of amplification in gastric cancer samples." (PMID 23717612, 2013). "MYC protein overexpression was previously detected in intestinal metaplasia and neoplastic tissue from all patients with intestinal type gastric cancer." (PMID 21811552, 2011). "MYC nuclear immunoreactivity was observed only in the intestinal metaplasia and gastric cancer biopsies." (PMID 21811552, 2011). "The oncogene c-MYC, frequently dysregulated in gastric cancer, has been shown to significantly enhance Reptin expression." (PMID 20509972, 2010). "Our findings demonstrate that FMR1 promotes gastric cancer cell proliferation, migration, and invasion through c-MYC signaling, suggesting that FMR1 may serve as a potential prognostic biomarker and therapeutic target for gastric cancer." (PMID 41184982, 2025). "Similarly, in gastric cancer, let-7b mimics reverse multidrug resistance and restores chemosensitivity by downregulating c-MYC and Lin28 expression, thereby promoting CSC differentiation." (PMID 41303548, 2025). "Additionally, prior research has shown that c-MYC induces the invasion and migration of gastric cancer cells by upregulating CDC25B and downregulating YWHAE expression." (PMID 41184982, 2025). "The unannotated compound in Cluster 1, GSK‐1059615, is identified as a PI3K and MTOR dual inhibitor which, in gastric cancer cells, potently inhibited cell growth, survival, proliferation, and the cell cycle potentially decoupling MYC from its control over cell proliferation." (PMID 41025936, 2025). "Similarly, GLCC1 upregulation enhances the interaction between IGF2BP1 and MYC, further strengthening MYC stability and driving gastric cancer development." (PMID 41361062, 2025). "Given our finding that FMR1 promotes malignant phenotypes of gastric cancer cells through activation of the c-MYC pathway, targeting key molecules along this axis may represent a potential therapeutic strategy." (PMID 41184982, 2025). "Additionally, emerging evidence indicates that LIN28B promotes oncogenesis in gallbladder carcinoma, gastric carcinoma, and multiple myeloma via MYC transcriptional activation." (PMID 40740861, 2025). "Additionally, YBX1 induces aerobic glycolysis by activating protein expression of HIF-1α and MYC in gastric cancer cells 46-48." (PMID 38948065, 2024). "In order to further validate whether NCAPD3 directly targets CCND1, ESR1, and MYC to regulate gastric cancer cell proliferation, Co-IP experiments were conducted to examine if NCAPD3 directly interacts with CCND1, ESR1, and MYC." (PMID 38711992, 2024). "Thus, circABCB10 up-regulates MYC expression by sponging miR-1252-5p and promotes the proliferation, invasion, and clonal formation of gastric cancer cells." (PMID 39727990, 2024). "A MYC/miR-22-3p/PHF8 regulatory axis has been identified in gastric cancer." (PMID 39311138, 2024). "Therefore, the relationship between METTL3 and MYC in gastric cancer is still unclear and still needs further exploration." (PMID 39678510, 2024). "HBXIP promotes the progression of gastric cancer via METTL3-mediated MYC mRNA m6A modification." (PMID 36891150, 2023). "DDX6 is implemented in the regulation of MYC expression in gastric cancer." (PMID 37019990, 2023). "In addition, our study demonstrated that GDF15 is involved in cell proliferation, migration, and invasion in gastric cancer via STAT3/MYC signaling." (PMID 36769245, 2023). "In addition, YWHAE silencing induces cell proliferation, invasion and migration through the upregulation of CDC25B and MYC in gastric cancer cells." (PMID 35515139, 2022).